DDR2 (discoidin domain receptor tyrosine kinase 2)
Diseases named in the same sentence as DDR2 in open-access papers (continued):
Sharing a sentence is not in itself a finding about the gene and the disease.
renal fibrosis (1 paper, 2021). A final common manifestation of a wide variety of chronic kidney diseases characterized by glomerulosclerosis and tubulointerstitial fibrosis. "We measured the expression of renal fibrosis markers α-Sma, Tgf-β and Col1a1 in CON ASO- and DDR2 ASO-treated AS mice." (PMID 33706638, 2021). "However, Masson-trichrome staining revealed that DDR2 ASO did not improve renal fibrosis." (PMID 33706638, 2021). "We found here that DDR2 ASO did not improve AS pathology such as proteinuria and renal fibrosis." (PMID 33706638, 2021).
serous ovarian cancer (1 paper, 2021). "Immunohistochemical detection of DDR2 in high-grade serous ovarian cancer (HGSOC) found DDR2 up-regulation in 14.10% (11 of 78) of cases." (PMID 34805157, 2021).
Stroke (1 paper, 2010). Sudden impairment of blood flow to a part of the brain due to occlusion or rupture of an artery to the brain. "Ddr2 (CD167b), a collagen adhesive receptor that participates in matrix integrin signaling, was increased 145-fold over naïve BMSC in our study, suggesting that Ddr2 matrix signals may contribute to post-stroke remodeling." (PMID 20509949, 2010).
T-cell lymphoma (1 paper, 2025). "Additionally, DDR2 regulates T-cell lymphoma apoptosis via the miR-615-5P/DDR2 pathway in lysosomal-associated membrane protein 1 (Circ-LAMP1) modulation." (PMID 40563472, 2025).
thymic carcinoma (1 paper, 2022). Thymic carcinoma (TC) is a type of thymic epithelial neoplasm characterized by a high malignant potential. "In this study, frequently mutated genes in thymic carcinomas included KIT, DDR2, PDGFRA, ROS1, and IGF1R." (PMID 35884448, 2022).
type 2 diabetes mellitus (1 paper, 2025). A type of diabetes mellitus that is characterized by insulin resistance or desensitization and increased blood glucose levels. "A Spearman correlation analysis showed 3110045C21Rik and Ddr2 expression occur together in type 2 diabetes mellitus (T2DM) patients, which indicates 3110045C21Rik regulates insulin-signaling mechanisms." (PMID 40649811, 2025).
urinary bladder urothelial carcinoma (1 paper, 2016). "An immunohistochemistry analysis and H-score calculation were performed to determine DDR2 expression in 340 urinary tract urothelial carcinoma and 295 urinary bladder urothelial carcinoma." (PMID 27793038, 2016).
uterine prolapse (1 paper, 2023). Downward displacement of the UTERUS. "Discoidin domain receptor-2 (DDR-2) promotes utse-seam attachment and protects against uterine prolapse." (PMID 37405383, 2023). "Taken together, these results indicate that DDR-2 protects against uterine prolapse and may play a role in mediating utse-seam BM-BM attachment." (PMID 37405383, 2023). "Supporting a functional role for DDR-2 in promoting INA-1-mediated utse-seam attachment, ddr-2 null mutants strongly enhanced the utse-seam detachment and uterine prolapse defect (Rup phenotype) of animals with reduced INA-1 function." (PMID 37405383, 2023). "Loss of C. elegans rap-1 has not been reported to have a Rup/uterine prolapse phenotype and we found that DDR-2 did not promote talin recruitment to the utse-seam connection." (PMID 37405383, 2023).
tumor (118 papers, 2007 to 2026). "Multiple studies have demonstrated a significant clinical association between discoidin domain receptors (DDR1/DDR2) and tumor progression." (PMID 40563472, 2025). "It has been reported that collagen type XI binds to integrin α2β1 and discoidin domain receptor tyrosine kinases 2 (DDR2) in cancer-associated fibroblasts, inhibiting cancer-associated fibroblast-mediated collagen remodeling and tumor cell invasion." (PMID 40554768, 2025). "DDR2 signaling in multiple preclinical tumor models has been shown to impact tumor progression and metastasis, and high DDR2 expression in human tumor specimens has been associated with worse clinical outcomes." (PMID 37996700, 2024). "For instance, the DDR1 or DDR2 activation mediated by collagen positively regulates the metastatic process involving tumor-associated neutrophils (TANs) and CAFs." (PMID 39769286, 2024). "For example, DDR2 in breast cancer-associated fibroblasts (CAFs) increases tumor stiffness by organizing type I collagen fibrils." (PMID 38222874, 2023). "We identified that collagen-receptor, DDR2, is an upstream regulator of periostin in cancer-associated fibroblasts and that this interaction promotes tumor metastasis." (PMID 35884543, 2022). "Paracrine actions of DDR2 in tumor cells and cancer-associated fibroblasts (CAFs) also support tumor invasion, migration and lung colonization in vivo." (PMID 34477203, 2021). "Some mutations such as E655K play a role in tumor progression by weakening the growth-inhibitory effect induced by collagen via DDR2, while V582E or L595F mutations also increase colony size in vitro." (PMID 33917302, 2021). "This expanding cluster contained two missense variants of consequence, a K/N substitution in the receptor tyrosine kinase DDR2 as well as a splice-site variant in the tumor suppressor RNF43." (PMID 34016182, 2021). "This DDR2 mutation was also validated with the Oncomine panel at high MAF in the 4 sectors with sufficient tumor tissue remaining for reanalysis." (PMID 32158697, 2020). "This pattern corresponds to a benign or less aggressive tumor associated collagen signature (TACS1) of which there was a significant increase in Ddr2-/- FSP1cre tumors." (PMID 31144616, 2019). "In conclusion, DDR2 overexpression is independently associated with tumor progression and dismal survival in UC patients." (PMID 27793038, 2016). "It has been shown that tumor cells with oncogenic DDR2 gene mutation can be effectively inhibited by multikinase inhibitors." (PMID 25173530, 2014). "Notably, coinjection of DDR2-deficient CAFs expressing POSTN with ovarian tumor cells led to a significant increase in tumor burden." (PMID 38903506, 2024). "To determine how tumor-associated stromal expression of DDR2 affected tumor burden, we performed targeted mRNA expression profiling of ID8TB−/− tumors dissected from WT and Ddr2−/− mice using the Nanostring nCounter Tumor Signaling 360 panel which includes 760 genes and 20 internal reference genes." (PMID 37996700, 2024). "Additionally, Discoidin domain Receptor 2 (DDR2), a tyrosine kinase, is considered as a biomarker, as its mutation promotes tumor growth, particularly in 30% of squamous NSCLC." (PMID 37444584, 2023). "First, we looked for genes whose expression pattern is consistently associated with the expression pattern of DDR2 in human tumors since these may conceivably be members of signaling pathways that a tumor could use to escape DDR2 depletion." (PMID 33247183, 2020). "Indeed, FIB-SEM analysis revealed that within 2–5 microns of the tumor-stromal interface there was less collagen and the collagen fibers present in Ddr2 deficient tumors were thinner and appeared more fragmented." (PMID 31144616, 2019). "Strikingly, DDR2 ability to interpret collagen cues is co-opted by tumor cells that exploit DDR2 signaling to activate pathways (e.g., MAPK and Hippo pathway) to sustain invasion and metastasis." (PMID 41492134, 2026).
tumor (continued). "In oral squamous cell carcinoma, gene editing of the colon cancer-associated transcript 1 (CCAT1) inhibits the DDR2/ERK/AKT pathway, leading to cell cycle arrest and tumor growth suppression." (PMID 40563472, 2025). "Heat shock protein HSP47 has been shown to bind and stabilize DDR2, thereby promoting tumor invasion." (PMID 40563472, 2025). "DDR2 also enhances tumor stiffness by reorganizing collagen fibers and recruiting Talin1 and Kindlin2 through the activation of Rap1, facilitating the full activation of integrins bound to collagen." (PMID 40563472, 2025). "Targeting DDR2 has been shown to enhance T-cell infiltration, improving tumor response to PD-1 immunotherapy." (PMID 40563472, 2025). "Knocking out discoidin domain receptor 2 (DDR2), a collagen receptor, prevented tumor organoids from responding to fluid flow." (PMID 41323575, 2025). "Collagen-activated DDR2 leads to G0/G1 phase cell cycle arrest and inhibition of fibrosarcoma cell proliferation, exhibiting tumor-suppressive functions." (PMID 40563472, 2025). "Tumor cell invasion was decreased in the presence CAF conditioned media (CM) depleted of DDR2 or arginase-1, and this invasion defect was rescued in the presence of CM from DDR2-depleted CAFs that constitutively overexpressed arginase-1." (PMID 37996700, 2024). "We have previously shown that SNAIL (SNAI1), an EMT inducing transcription factor that promotes tumor cell migration and invasion, is regulated by the action of DDR2 in tumors, post-transcriptionally." (PMID 37996700, 2024). "Here we report that DDR2 regulates collagen protein production by CAFs in the tumor microenvironment by controlling the transcription of arginase-1." (PMID 37996700, 2024). "There was a strong correlation between DDR2 expression in the tumor stroma and POSTN expression in the stromal cells of OC patients." (PMID 38903506, 2024). "It is well known that the content and morphology of collagens in tumor tissues are drastically altered following chemotherapy, and discoidin domain receptor 2 (DDR2) is a unique type of receptor tyrosine kinase (RTK)." (PMID 39766183, 2024). "Some fibrillar collagens suppress tumor growth by interacting with Discoidin Domain Receptor 2 (DDR2), a transmembrane receptor tyrosine kinase (RTK)." (PMID 39769286, 2024). "We found that although DDR2 is expressed by a subset of tumor cells in human tumor specimens, the majority of DDR2 expression was in CAFs." (PMID 37996700, 2024). "The action of DDR2 in CAFs can influence fibrillar collagen mRNA levels and can mechanically remodel tumor ECM collagen fibers via integrin regulation." (PMID 37996700, 2024). "Recurrent breast cancer epithelial-mesenchymal transformation (EMT) regulatory factors TWIST and SNAIL induce tumor cell ferroptosis significantly in a DDR2-dependent manner." (PMID 39664391, 2024). "We showed that, based on the differential high expression, inhibition of either MAP2K1 or DDR2 reduced tumor growth, and a combination therapy almost completely suppressed tumor growth." (PMID 38554776, 2024). "High expression of DDR2 in experimental mouse tumor models leads to increased tumor metastasis, and in various human tumors is associated with poor survival." (PMID 37996700, 2024). "In both, DDR2 was found to be primarily expressed in CAFs but was also present in some tumor cell clusters." (PMID 37996700, 2024). "A limitation of our study is that we used mice with host global DDR2 knockout for our in vivo tumor burden studies." (PMID 37996700, 2024). "Collectively, these results suggest that ECM-induced biomechanical force promotes tumor cell quiescence through DDR2/STAT1 signaling." (PMID 37369642, 2023). "Discoidin domain receptor 2 (DDR2), a fibrillar collagen receptor, is present on both tumor cells and CAFs." (PMID 36980785, 2023). "WRG-28 has also been shown to inhibit tumour invasion and metastasis as a selective DDR2 small-molecule inhibitor." (PMID 37007062, 2023).
tumor (continued). "In both cases, evidence was presented that DDR2 functioned in concert with collagen-binding β1 integrins to stimulate, on one hand, tumor metastasis to the lungs or, on the other, ectopic bone formation." (PMID 38222874, 2023). "DDR2 is also expressed on subpopulations of tumor myeloid cells and drives myeloid inflammatory pathways via RTK signaling." (PMID 37662958, 2023). "After FAP was removed from CAFs by CRISPR/Cas9-mediated gene knockout, the expression of DDR2 was down-regulated, tumor hardness decreased, and the process of carcinogenesis in vivo and in vitro was inhibited." (PMID 37978384, 2023). "We identified that POSTN had significantly higher expression in the DDR2-expressing NOFs co-cultured with ES2 tumor cells compared to conditioned media of NOF alone or DDR2-depleted NOFs co-cultured with ES2 tumor cells." (PMID 35884543, 2022). "DDR2-depleted CAFs co-cultured with ES2 tumor cells had further reduction in POSTN levels compared to DDR2-expressing CAFs co-cultured with ES2 cells." (PMID 35884543, 2022). "The ability of DDR2 to bind to collagen promotes protumoral responses in cancer cells that influence the tumor microenvironment (TME)." (PMID 35711892, 2022). "In this regard, increased DDR2 promotes tumor aggressiveness in the breast, by means of enhanced proliferation, migration, colony formation, and metastasis." (PMID 35711892, 2022). "Overexpression of POSTN in DDR2-depleted CAFs (CAF shDDR2 POSTN OE + ES2) led to increased tumor burden in our xenograft model." (PMID 35884543, 2022). "Given the role of DDR2 in cancer metastasis, studying the downstream networks that are regulated by this tyrosine kinase in tumor and stroma is important." (PMID 35884543, 2022). "Comparably, we uncover a plausible positive interrelation between the levels of DDR2 and the mobilization of CAFs and TAMs into the tumor foci, which points out to DDR2 as a possible regulator of attracting signals for these cell populations." (PMID 35711892, 2022). "One of the receptors involved in the tumor-ECM interplay is the discoidin domain receptor 2 (DDR2), an atypical RTK, due to its capacity to bind collagens." (PMID 35711892, 2022). "Mice injected with DDR2-depleted CAFs (CAF shDDR2 + ES2) had decreased tumor burden compared to mice injected with DDR2-expressing CAFs (CAF shSCRM + ES2)." (PMID 35884543, 2022). "DDR1 or DDR2 is known to control tumor cell proliferation and invasion, depending on the tumor type and the nature of the microenvironment." (PMID 34957688, 2022). "In our in vivo study, we show a decrease in tumor burden in mice injected with DDR2-depleted CAFs (CAF shDDR2 + ES2) had decreased tumor burden compared to mice injected with DDR2-expressing CAFs (CAF shSCRM + ES2)." (PMID 35884543, 2022). "Our findings showed that, together with the expected overexpression of TME markers, DDR2 was upregulated in tumor samples." (PMID 35711892, 2022). "Conditioned media from DDR2-depleted CAFs showed decreased ability to induce ES2 tumor cell migration and proliferation." (PMID 35884543, 2022). "We aimed to define the role of DDR2′s modulation of POSTN in CAFs on tumor cell invasion into the basement membrane and ECM migration." (PMID 35884543, 2022). "DDR2 and periostin signaling in CAFs promotes tumor migration, clearance, proliferation, and invasion." (PMID 35884543, 2022). "As a recognized critical regulator of EMT, DDR2 upregulation has been confirmed in many tumor cell lines and takes part in the interaction with the extracellular matrix, the regulation of cell motility and adhesion, and metastatic spreading." (PMID 35012558, 2022). "Overexpression of POSTN in DDR2-depleted CAFs led to an increased ability to promote tumor cell migration and proliferation." (PMID 35884543, 2022). "Then, DDR2 status correlation with tumor aggressiveness and patient survival were retrieved from different databases." (PMID 35711892, 2022).
tumor (continued). "Given the importance of DDR2 in invasive BC process, we evaluated collagen and DDR2 status in tumor samples compared to healthy adjacent tissue, together with DDR2 implication on metastasis progression." (PMID 35711892, 2022). "We first identified that tumor cells co-cultured with DDR2-expressing fibroblasts had lower periostin expression when compared to tumor cells co-cultured with DDR2-depleted fibroblasts." (PMID 35884543, 2022). "In order to determine the role of DDR2′s modulation of POSTN on tumor cell spreading and proliferation, we performed spheroid spreading and wound healing assays." (PMID 35884543, 2022). "For this reason, we aim to evaluate the correlation between intratumoral expression of DDR2 and the infiltration of the main TME cell populations, cancer-associated fibroblasts (CAFs), and tumor-associated macrophages (TAMs)." (PMID 35711892, 2022). "This goes in line with the immunohistochemical analysis, in which we observe DDR2 expression in the tumor stroma of BC tissue slides." (PMID 35711892, 2022). "To determine if DDR2′s regulation of periostin in CAFs influences tumor metastasis in cell-based assays, we performed attachment, clearance, and invasion assays." (PMID 35884543, 2022). "In both the Matrigel transwell invasion and 3D collagen migration assays, we observed decreased tumor cell invasion in the DDR2-depleted CAF condition compared to DDR2-expressing CAFs." (PMID 35884543, 2022). "To determine the effect of DDR2′s modulation of POSTN on tumor cell migration and proliferation, we performed wound healing assays with ES2 tumor cells and CAF conditioned media." (PMID 35884543, 2022). "In tumor stromal cells (such as CAFs), DDR2 remodels the tumor stromal ECM into a more invasion-permissive environment." (PMID 34477203, 2021). "K608E-rescued cells showed reduced pulmonary metastasis compared to that of parental control tumors (P<0.05), but increased pulmonary metastasis compared to that of DDR2-depleted tumor cells (P<0.05)." (PMID 34477203, 2021). "Conditioned medium from both human and mouse tumor cells rescued with K608E also enhanced tumor cell invasion through Matrigel, but only partially when compared to the effect of conditioned medium from WT DDR2-expressing tumor cells." (PMID 34477203, 2021). "DDR2 is of particular interest as its actions in both tumor cells and tumor stromal cells within the primary tumor environment contribute to metastasis regulation." (PMID 34477203, 2021). "We next evaluated the role of the paracrine activity of DDR2 in CAFs in supporting migration of tumor cells through 3D collagen I gels." (PMID 34477203, 2021). "The paracrine action of WT DDR2 and K608E.DDR2 in CAFs supported tumor cell invasion through Matrigel and migration (both single-cell and collective)." (PMID 34477203, 2021). "Here, we show that tyrosine kinase activity-independent action of DDR2 in tumor cells can support Matrigel invasion and in vivo metastasis." (PMID 34477203, 2021). "In the tumor microenvironment, CAFs produce DDR2, a collagen receptor, that mechanically reshapes extracellular matrix stiffness to facilitate tumor cells migration and metastasis." (PMID 34322780, 2021). "The tumor microenvironment(TME) of DDR2 patients was highly infiltrated by activated immune cells, immune checkpoint molecules and proinflammatory molecules and antigen presentation-related molecules." (PMID 34335575, 2021). "As previously reported, DDR2-depleted tumor cells had significantly reduced number of pulmonary metastases compared to that observed for control parental cells (expressing scrambled shRNA, shSCR) (P<0.001)." (PMID 34477203, 2021). "Conditioned medium from K608E-rescued CAFs rescued, partially, tumor cell migration in collagen I gels, whereas medium from ΔKD-rescued CAFs failed to support migration through 3D collagen I (equivalent to DDR2-depleted CAFs)." (PMID 34477203, 2021).